ANAPC16 (anaphase promoting complex subunit 16)
Description:
Component of the anaphase promoting complex/cyclosome (APC/C), a cell cycle-regulated E3 ubiquitin ligase that controls progression through the cell cycle. APC/C acts by mediating ubiquitination and subsequent degradation of target proteins: it mainly mediates the formation of 'Lys-11'-linked polyubiquitin chains and, to a lower extent, the formation of 'Lys-48'- and 'Lys-63'-linked polyubiquitin chains. APC/C catalyzes assembly of branched 'Lys-11'-/'Lys-48'-linked branched ubiquitin chains on target proteins. APC/C is activated by CDC20 in the metaphase/anaphase transition of cell cycle, targeting the degradation of cyclin B and securin. APC/C is regulated by the mitotic checkpoint complex (MCC), which inhibits APC/C and delays chromosome segregation.
Synonyms: APC16; C10orf104; CENP-27; bA570G20.3; FLJ33728; MSAG
Tractability: PROTAC: ubiquitination databases record sites on it.
Gene: Protein-coding gene on chromosome 10 (72,215,863 to 72,235,860, forward strand). Ensembl gene ENSG00000166295.
Subcellular location: Cytoplasm; Nucleus; Chromosome, centromere, kinetochore
Subcellular location (Human Protein Atlas): Cytosol
Pathways (Reactome):
Cell Cycle: APC-Cdc20 mediated degradation of Nek2A; APC/C:Cdc20 mediated degradation of Cyclin B; APC/C:Cdc20 mediated degradation of Securin; APC/C:Cdc20 mediated degradation of mitotic proteins; APC/C:Cdh1 mediated degradation of Cdc20 and other APC/C:Cdh1 targeted proteins in late mitosis/early G1; Autodegradation of Cdh1 by Cdh1:APC/C; Cdc20:Phospho-APC/C mediated degradation of Cyclin A; Conversion from APC/C:Cdc20 to APC/C:Cdh1 in late anaphase; Inactivation of APC/C via direct inhibition of the APC/C complex; Phosphorylation of the APC/C; Regulation of APC/C activators between G1/S and early anaphase; Separation of Sister Chromatids
DNA Replication: Assembly of the pre-replicative complex; CDK-mediated phosphorylation and removal of Cdc6
Cellular responses to stimuli: Senescence-Associated Secretory Phenotype (SASP)
Disease: Aberrant regulation of mitotic exit in cancer due to RB1 defects
Gene expression (Transcription): Transcriptional Regulation by VENTX
Gene Ontology:
Molecular function: protein binding
Biological process: anaphase-promoting complex-dependent catabolic process; protein branched polyubiquitination; protein K11-linked ubiquitination; protein K48-linked ubiquitination; protein ubiquitination; regulation of meiotic cell cycle; regulation of mitotic cell cycle
Cellular component: anaphase-promoting complex; cytoplasm; cytosol; kinetochore; nucleus; nucleoplasm
Genetic constraint (gnomAD): Loss-of-function variants: 5 observed, 12.41 expected, observed/expected ratio (o/e) 0.4, 90% interval 0.21 to 0.85. The upper end of that interval is the gene's LOEUF score, 0.85, which puts it in group 3 of 6, group 1 being the genes least tolerant of losing a copy. Missense variants: 113 observed, 134.07 expected, observed/expected ratio (o/e) 0.84, 90% interval 0.72 to 0.99. Synonymous variants: 55 observed, 54.02 expected, observed/expected ratio (o/e) 1.02, 90% interval 0.82 to 1.27.
Homologues: Orthologues: chimpanzee ANAPC16 (100% identical), dog ANAPC16 (100% identical), macaque ANAPC16 (100% identical), mouse Anapc16 (100% identical), rabbit ANAPC16 (100% identical), pig ANAPC16 (99% identical), guinea pig ANAPC16 (98% identical), rat Anapc16 (98% identical), tropical clawed frog anapc16 (95% identical), zebrafish anapc16 (86% identical).
Diseases named in the same sentence as ANAPC16 in open-access papers:
ANAPC16 is named in the same sentence as 1 disease in open-access papers, as found by Europe PMC text mining. Sharing a sentence is not in itself a finding about the gene and the disease.
ANAPC16 shares sentences with these, for which no sentence is quoted: asthma (1 paper).